CXCL10 (C-X-C motif chemokine ligand 10)
Diseases named in the same sentence as CXCL10 in open-access papers (continued):
Sharing a sentence is not in itself a finding about the gene and the disease.
autoimmune disease (continued). "CXCL10 was reported to be elevated in several autoimmune diseases, including autoimmune thyroiditis, Graves disease, type 1 diabetes (T1D), systemic lupus erythematosus (SLE), localized scleroderma, and RA." (PMID 27964744, 2016). "C-X-C motif chemokine 10 (CXCL10) is a chemokine that plays a critical role in the infiltration of T cells in autoimmune diseases and is reported to be expressed in muscle tissue of polymyositis." (PMID 24939012, 2014). "Not only circulating levels of CXCL10 but also the tissue expression was increased in various autoimmune diseases including rheumatoid arthritis, systemic lupus erythematosus, systemic sclerosis, type I diabetes mellitus and autoimmune thyroid disease." (PMID 24939012, 2014). "Of further interest, the expression of CXCL10 is increased in autoimmunity diseases like rheumatoid arthritis and multiple sclerosis." (PMID 23841502, 2013). "Second: The unique expression of CXCL10 after LCMV infection of the pancreas imprints on one hand a pattern for the subsequent development of autoimmune disease and neutralization of this one single key factor precludes disease." (PMID 23675028, 2007). "Key inflammatory mediators, such as TNFα or CXCL10, play a dual role in the development of autoimmune disease, depending on the time and location of their expression." (PMID 23675028, 2007). "Accordingly, it may be important to consider the use of anti-CXCR3 and anti-CXCL10 treatments, both of which are now being used in the clinical setting for attenuating autoimmune disease." (PMID 41273416, 2026). "Recent studies have shown that CXCL10 expression is increased in the serum and/or tissues of patients with various autoimmune diseases (e.g., rheumatoid arthritis, systemic lupus erythematosus, desiccation syndrome, systemic sclerosis, and idiopathic inflammatory myopathies)." (PMID 40540498, 2025). "The serum and/or tissue expressions of CXCL10 in various autoimmune diseases." (PMID 38376769, 2024). "CXCL10, a chemokine, contributes to the pathogenesis of autoimmune diseases." (PMID 38881847, 2024). "The CXCL10, also known as IFN-γ-inducible protein 10 (IP-10), through its receptor [chemokine (C-X-C motif) receptor 3 (CXCR3)], is implicated in the immune-pathogenesis of numerous autoimmune diseases, (i.e., GD and orbitopathy, type 1 diabetes, mixed cryoglobulinemia, SLE, SS, or SSc)." (PMID 35837308, 2022). "Moreover, recent reviews suggested that chemokines, CXCL10, CXCL9, and CXCL11, are implicated in the pathogenesis of autoimmune diseases such as autoimmune thyroiditis, type 1 diabetes, Graves disease, Thyroid eye disease, and Addison’s disease." (PMID 34054797, 2021). "Moreover, recent reviews suggested that the chemokines, CXCL10, CXCL9, and CXCL11, are implicated in the pathogenesis of autoimmune diseases such as autoimmune thyroiditis, T1DM, Graves disease, Thyroid eye disease, and Addison’s disease." (PMID 35242125, 2021). "Moreover, the alteration of CXCL10 has been related to pathogenesis during chronic inflammation, infectious and autoimmune diseases." (PMID 31737787, 2019). "CXCL10 expression is dependent on IFN-γ and is implicated in several autoimmune disorders." (PMID 30795559, 2019). "IP-10 (CXCL10) is a small protein described as an “inflammatory chemokine” crucial to leukocyte trafficking as well as the perpetuation of inflammation in MS and various other autoimmune diseases." (PMID 29420590, 2018). "CXCL10 is a powerful chemo-attractant for both CD4+ and CD8+ T cells to the site of inflammation, and is expressed in various Th1 type inflammatory diseases, and has also been implicated in autoimmune disease." (PMID 24134207, 2013). "However, abrogation or attenuation of chemokine induction (CXCL10, IP-10, inflammatory cytokines) at an auxiliary location would be likely to impair the onset of autoimmune disorder." (PMID 16759382, 2006).
autoimmune disease (continued). "CCL2 and CXCL10 are classic chemokines that can chemoattract lymphocytes and monocyte macrophages to infiltrate target organs, which are involved in the initiation of immune response and acceleration of the inflammation development and are related to many autoimmune diseases, including HT." (PMID 36874364, 2023). "Thus, CXCL10 can also act as a bystander effector that expands an autoaggressive immune response, which may result in autoimmune disease." (PMID 24586509, 2014). "Recent reports have shown that serum and/or tissue expressions of CXCR3 and CXCL10 are increased in various autoimmune diseases, which may have important roles in leukocyte homing to inflamed tissues and in the perpetuation of inflammation, and therefore, tissue damage." (PMID 21647407, 2011). "But given its role in other autoimmune diseases and the relationship with CXCL9 and CXCL10, we also included CXCL11 in our study as a potential pathogenic factor." (PMID 39981245, 2025). "CXCL10, or IFN-γinducible protein 10(IP-10), a chemokine released by IFN-γ stimulated endothelial cells, plays a role in autoimmune diseases." (PMID 39104393, 2024). "Both HT and PsA are autoimmune diseases mediated by Th1 cell immunity, with Th1 cells, interferon-gamma (IFN-γ), and the chemokine CXCL10 playing pivotal roles in their pathogenesis." (PMID 39119335, 2024). "This suggests that CXCL10 and CXCL11 are indicators of disease progression, warranting further investigation into their roles in autoimmune disorders beyond pSS." (PMID 38900301, 2024). "CXCL10 and its receptor CXCR3 play a role in the pathogenesis of many autoimmune diseases, and both proteins are expressed on various cells." (PMID 35269967, 2022). "Our results on the effect of miR-15a-5p on CXCL10 in ECD are supported by reports that miR-15a-5p also modulates neoplastic and immune/inflammatory characteristics in CML and in the autoimmune disease myasthenia gravis." (PMID 34785791, 2022). "Chemokine CXCL10 is a powerful recruiter of Th1 cells expressing CXCR3 into target tissues, which is responsible for organ-specific autoimmune diseases." (PMID 34659199, 2021). "It has been widely reported in the literature that many cytokine and chemokine genes (e.g., TNF-a, IL-8, CXCL2, CXCL3, CXCL10, LIF, IL-17C and IL-23A) are the basis of autoimmune disorder pathways that are characterized by inflammation." (PMID 28099447, 2017). "Increased expression of CXCL10 and CXCR3 was shown in various autoimmune diseases, and they play fundamental parts in leukocyte homing into the inflamed tissues to accelerate the process of tissue damage." (PMID 29456788, 2017). "Binding of CXCL10 chemokines and CXCR3 plays a vital role in Th immune response, which is responsible for organ-specific autoimmune diseases." (PMID 29383139, 2017). "Among the large chemokine and chemokine receptor families, CXCR3 and CXCR3-binding chemokines CXCL10 and CXCL9 and ITAC/CXCL11 are key players in the maintenance and amplification of the autoimmune disease." (PMID 26892362, 2016). "Among these, CXCL10 notably relies on IFN-γ for secretion, playing a pivotal role in promoting Th1 cell activation and amplifying inflammation through CXCR3-mediated feedback loops, thereby significantly influencing immune regulation in autoimmune diseases." (PMID 38900301, 2024). "In this study, we found a significant positive correlation between CXCL10 levels and serum ferritin in PMR patients, which belongs to the acute time-phase response proteins and is elevated in acute inflammation, malignancy, autoimmune diseases, and infections." (PMID 39476056, 2024). "CXCL10, a chemokine that binds to its specific receptor C-X-C motif chemokine receptor 3 (CXCR3), mobilizes and activates immune cells such as T cells, monocytes, and NK cells in specific tissues, playing a crucial role in tissue damage in autoimmune diseases." (PMID 39185418, 2024).
autoimmune disease (continued). "Interestingly, the chemokine CXCL10, a ligand of CXCR3, was detected and appear to contribute to the pathogenesis of various autoimmune disease." (PMID 36591302, 2022). "In autoimmune diseases such as SLE, increased expression of chemokine receptors (CXCR2, CXCR3, CCR3 and CCR1) and elevated levels of chemokines such as MCP-1/CCL2, MIP-1/CCL-4, SDF-1/CXCL-12, RANTES/CCL5 and IP-10/CXCL-10 are observed." (PMID 36059466, 2022). "Moreover, CXCL10 is involved in the pathogenesis and progression of infectious diseases (i.e., Mycobacterium tuberculosis) or HCV-related autoimmune disorders, sepsis, or HIV." (PMID 31485460, 2019). "CXCL-10, also named as interferon gamma-induced protein 10 (IP-10), is a member of CXC chemokines and known as activator on antitumor, antiviral, antifungal, and autoimmune diseases." (PMID 24696007, 2014). "Currently, there are several anti-CXCL10 monoclonal antibodies and anti-CXCR3 molecule blockades that are being investigated in clinical trials for autoimmune diseases such as rheumatoid arthritis; however, the therapeutic efficacies of these antagonists in vitiligo patients are currently unknown." (PMID 35096274, 2022). "Among them, CXCR3 and its chemokines CXCL10, CXCL9, and CXCL11 are widely involved in the pathogenesis of autoimmune diseases such as HT, GD, thyroid eye disease (TED), type 1 diabetes, and autoimmune Addison’s disease, and may be potential targets for new drugs to treat these diseases." (PMID 35720300, 2022). "In addition, IL-27 can also increase the content and ratio of Th1 and Th17 cells, thus leading to the excessive secretion of inflammatory mediators in local tissues, such as IFN-γ, CXCL10, and TNF-α, Thereby forming an inflammatory cascade that eventually induces autoimmune diseases." (PMID 34691022, 2021). "In addition, both CXCL10 and VEGF have been described to be potential biomarkers for various diagnoses such as chronic obstructive pulmonary disease (COPD) and non-small cell lung cancer and for exacerbations of autoimmune diseases." (PMID 34691031, 2021). "Therefore, we speculate that CXCL10 could be a potential intervention target for preventing IPF in patients with hypothyroidism and emphasize that chemokines may be intermediary factors in how autoimmune diseases affect other systemic diseases." (PMID 39185418, 2024). "Interestingly, CXCL10 release, identified in this investigation as a robust marker of TLR7/8 immune activation, has also been shown to be part of an amplification feedback loop driven by IFNγ and TNFα release from Th1 lymphocytes in a variety of autoimmune diseases." (PMID 35261923, 2022). "Although the experimental model of infectious disease (e.g., malaria and sepsis) and autoimmune disease (e.g., RA and SLE) indicates that artemisinin-family drugs could target the inflammatory networks to decrease the levels of cytokines (e.g., IL-6 and TNF-α) and chemokines (e.g., IL-8, CXCL10)." (PMID 32754163, 2020).
influenza (116 papers, 2007 to 2026). An acute viral infection of the respiratory tract, occurring in isolated cases, in epidemics, or in pandemics; it is caused by serologically different strains of viruses (influenzaviruses) designated A, B, and C, has a 3-day incubation period, and usually lasts for 3 to 10 days. "We report that both CXCL8 and CXCL10 modulate the pathways associated with influenza infection, such as the Toll-like receptor signalling pathway, Influenza A, and the RIG-I-like receptor signalling pathway." (PMID 37515084, 2023). "Influenza infection increased IL-6, IL-8, IL-10, and CXCL-10 secretion, consistent with previous reports." (PMID 40929365, 2026). "CXCL10 significantly decreased in the influenza MASLD group (Δ = 3333, 95% CI 1368-5299), and the difference compared to non-MASLD was found to be significant (p = 0.0167)." (PMID 40869413, 2025). "Different cytokine profiles were observed compared to influenza and bacterial pneumonia, with IL-2, IL-1β, IL-8, IL-10, CXCL10, and MCP-1 being highest in the AdV group, while free TGF-β1 was lowest in the AdV group." (PMID 39858309, 2025). "Plasma concentrations of CXCL10 have also been reported to be higher in SARS-CoV-1 and influenza infections, and closely related to a fatal risk in ARDS associated with influenza A (H1N1) infection." (PMID 38584257, 2024). "As expected, CXCL10 and IFNα levels were highest in influenza infection, whereas IL6, IL10, IL1β, and PROK2 (which is highly inducible in macrophages by LPS and other TLR2/4 agonists) reached higher levels in the bacterial infections." (PMID 39395995, 2024). "We observed increased expression of Stat1, Stat2, Mx1, Oasl2, CCL2, CCL3, CXCL9, and CXCL10 in influenza-infected hearts and lungs when compared to PBS-treated controls." (PMID 38750107, 2024). "CCL5 and CXCL10 have previously been identified to be important in the recruitment of Trm to the lungs in an influenza model." (PMID 39749186, 2024). "CXCL10 levels in culture supernatant were decreased by itaconate treatment of lung tissue after influenza infection." (PMID 38085578, 2023). "In contrast, several genes involved in the interferon-stimulated innate immune response (OAS1, OAS2, SOCS1, DDX58, 16 CXCL10) were upregulated following influenza superinfection during SARS-CoV-2 infection." (PMID 38178911, 2023). "CCL3 and CXCL10 are known to trigger the infiltration of macrophages in influenza infection yet, despite the decrease in these chemokines, there was no change in the number of macrophages in the infected NOX4 TG." (PMID 35601109, 2022). "The decrease in CXCL10 expression in the influenza-infected NOX4 TG mice compared to infected WT mice is consistent with both the decrease in neutrophil infiltration and the decrease in lung weight seen in infected NOX4 TG mice." (PMID 35601109, 2022). "In serum, CXCL10 has been shown to be upregulated in influenza patients and in SARS patients patients with ARDS." (PMID 35371005, 2022). "The activation of CXCR3 by CXCL10 triggers influenza-induced neutrophil infiltration, and the deletion of CXCL10 and CXCR3 results in increased survival." (PMID 35601109, 2022). "Influenza infected NOX4 TG mice had decreased expression of CXCL10, CCL3, CXCL1 and CXCL2 three days post infection." (PMID 35601109, 2022). "The side effects of CXCL10 blockade in immune protection against influenza and COVID19 should also be tested due to the functions of this chemokine in mobilizing T cells." (PMID 35674675, 2022). "Analysis of transcriptomic signatures revealed an increase of IP-10 (CXCL-10) during co-infection with RSV or influenza and bacteria, promoting the recruitment of immune cells and contributing to lung pathology." (PMID 34578306, 2021). "Expression of three cytokine indicators CCL2, CXCL10 and viral NA were selected to screen immunomodulators and antiviral agents for the treatment of influenza." (PMID 34955842, 2021).
influenza (continued). "Other chemokines elevated in influenza-infected Tpl2-/- mice, including CXCL10, CCL5, CCL3 and CCL4, are also overexpressed in human cases of lethal influenza infections and recognized for recruitment of inflammatory monocytes and neutrophils." (PMID 34691044, 2021). "Our study further indicated that rosiglitazone treatment decreased downstream signaling agents STAT1, STAT2, and the ISGs Mx1, CXCL9 and CXCL10 during influenza infection." (PMID 31159430, 2019). "In two other studies that evaluated correlates of protective immune responses to inactivated influenza vaccines with a systems vaccinology approach, levels of serum CXCL10 correlated with good humoral responders, i.e. production of neutralizing antibodies." (PMID 31871773, 2019). "Similar to IFN‐β and IFN‐λ1, IgG opsonization also suppressed influenza‐induced CXCL10 mRNA production." (PMID 30184252, 2018). "Through such approach, it has been reported that different animals (such as primates, ferrets and mice) with influenza infection have been induced extraordinarily high expression of cytokines and chemokines (e.g. CXCL10, CCL2 and CXCL9)." (PMID 21819625, 2011). "Notably, CCL2 and CXCL10 levels are abnormally elevated in certain fatal cases of influenza infection." (PMID 40626651, 2025). "Decreased expression of the IFN response genes Stat1, CXCL9, and CXCL10 may be due to suppression of the JAK/Stat signaling pathways in response to empagliflozin treatment during influenza infection." (PMID 38112660, 2023). "In influenza-infected lungs, CXCL10 is the major CD8 T cell recruiter." (PMID 38037190, 2023). "Likewise, influenza infection actively induces the cytokines’ expressions, like IL-6 and CXCL-10, and there is also a cell-autonomous relationship between influenza NS1 and Hh signaling." (PMID 35681469, 2022). "Of the 638 antiviral and inflammatory genes that were differentially expressed between lungs of uninfected macaques and macaques with lethal influenza, 541 (85%) were upregulated in response to infection, including inflammatory chemokines such as CXCL10 and CXCL13 and a cluster of IFN genes." (PMID 35271686, 2022). "CXCL9 and CXCL10 from epithelial cells are strongly induced by influenza infection." (PMID 32817719, 2020). "Indeed, we found that influenza infection strongly induced CXCL-10 and IL6 expression, the latter of which was partially enabled by a direct interaction between Hh signaling and NS1." (PMID 28837667, 2017). "Furthermore, when we compared nasal wash samples from influenza-infected patients with viral load ≥ 28 and increased IL-6 and CXCL10 to healthy controls, we identified 162 differentially-expressed proteins between the two groups." (PMID 27088501, 2016). "Influenza infection was associated with significant increases in virus-associated and inflammatory gene signatures, including CXC-motif chemokine ligand-10 or interferon gamma induced protein-10 (CXCL10/IP-10), a well-characterized influenza infection-induced inflammatory mediator." (PMID 41383614, 2025). "The production of several chemokines involved in influenza severity, including CCL2/MCP-1, CCL3/MIP-1α, CCL4/MIP-1β, CCL5/RANTES, CXCL2/MIP-2, and CXCL10/IP-10 was also quantified." (PMID 40612502, 2025). "Immunokinetic patterns were pathogen-specific, including transient increase in IL-17A and IL-10 in Legionella and Mycoplasma infections, and CXCL10, IL-2, IL-17A, TGF-β1 and IL-10 in influenza." (PMID 40869413, 2025). "In comparison to influenza and bacterial CAP, patients with AdV had higher serum IL-2, IL-1β, IL-8, IL-10, CXCL10 and MCP-1, and lower TGF-β1 concentration." (PMID 39858309, 2025). "In influenza, MASLD patients also displayed exaggerated interferon-induced chemokine CXCL10 and immunoregulatory TGF-β1 and IL-10 responses, possibly enhancing tissue damage and impairing viral clearance." (PMID 40869413, 2025).